SNORD19 (small nucleolar RNA, C/D box 19)
Synonyms: HBII-108
Gene: Small nucleolar RNA gene on chromosome 3 (52,689,248 to 52,689,315, forward strand). Ensembl gene ENSG00000212493.
Gene Ontology:
Biological process: RNA processing
Cellular component: nucleolus
Homologues: Orthologues: chimpanzee SNORD19 (100% identical), macaque SNORD19 (91% identical), rat Snord19 (91% identical), mouse Snord19 (88% identical), pig SNORD19 (88% identical), rabbit SNORD19 (87% identical), guinea pig SNORD19 (60% identical). Paralogues in human: SNORD19C (63% identical).
Diseases named in the same sentence as SNORD19 in open-access papers:
SNORD19 is named in the same sentence as 3 diseases in open-access papers, as found by Europe PMC text mining. Sharing a sentence is not in itself a finding about the gene and the disease. The quoted sentences say what the papers report.
ovarian carcinoma (1 paper, 2019). A malignant neoplasm originating from the surface ovarian epithelium. "Low expression of SNORA2B and SNORD19 is related to poor prognosis of ovarian cancer patients, and high expression of SNORD116-4 and SNORD89 is associated with poor prognosis of ovarian cancer patients." (PMID 31395064, 2019).
tumor (2 papers, 2019 to 2025). "Many ncRNA-based genes, such as MIR4737, CR381653.1, and SNORD19, are among the genes specifically expressed in TICs, suggesting the functional importance of ncRNAs in tumor initiation and stemness maintenance." (PMID 40862733, 2025). "Similar to SNORD123, SNORD19 has also been reported to have a different expression pattern in different tumor subtypes, implying its potential capacity for cancer subtyping." (PMID 31052553, 2019).
SNORD19 also shares sentences with these, for which no sentence is quoted: cancer (1 paper).